RNU6-1305P (RNA, U6 small nuclear 1305, pseudogene)
Gene: Small nuclear RNA gene on chromosome 5 (36,155,119 to 36,155,222, forward strand). Ensembl gene ENSG00000201223.
Homologues: Orthologues: chimpanzee U6 (96% identical), macaque U6 (88% identical), rat U6 (87% identical), guinea pig U6 (77% identical), dog U6 (66% identical). Paralogues in human: RNU6-11P (88% identical), RNU6-35P (88% identical), RNU6-37P (88% identical), RNU6-25P (87% identical), RNU6-393P (87% identical), RNU6-41P (87% identical), RNU6-812P (87% identical), RNU6-1 (86% identical), RNU6-15P (86% identical), RNU6-2 (86% identical), RNU6-20P (86% identical), RNU6-29P (86% identical), and 1292 more.